IL6 (interleukin 6)
Diseases named in the same sentence as IL6 in open-access papers (continued):
Sharing a sentence is not in itself a finding about the gene and the disease.
co-infection (continued). "Moreover, co-infection with all three strains of the red complex bacteria with F. nucleatum showed a remarkable increase in cytokine production, and treatment with LJLE significantly suppressed the IL-6 and IL-8 expression over the entire infection time course." (PMID 30142971, 2018). "Among them, co-infection with MVA-Δ3-ISG15AA consistently induced the highest cytokine expression, particularly for IL-6 and IFN-I, regardless of the co-infecting MVA-based antigen vector." (PMID 40733673, 2025). "IL-6, IL-8, and IL-10 levels in CML patients with bacterial and fungal coinfection were higher than those in patients without infection." (PMID 37114211, 2023). "In iPAM 3D4/21 cells, the co-infection with PCV2b and SwIV H1N1 did not significantly impact the IL-6 mRNA expression." (PMID 37243291, 2023). "During these co-infections involving C. albicans and Candida krusei, IL-6 and prostaglandin E2 (PGE2) were found to be significantly elevated, which was not the case in co-infections with other Candida species." (PMID 31623187, 2019). "Although levels of TNF-α and IL-6 following mono-infections were donor and MOI-dependent; production of these cytokines was significantly augmented during co-infections and this was not attributed to the increase in total MOI." (PMID 28644900, 2017). "Significantly higher levels of systemic and local interleukin-6 (IL-6), tumor necrosis factor alpha (TNF-α) and IL-1β have been found during the early stages of co-infection than during single infection, regardless of the morphogenesis of C. albicans." (PMID 28666415, 2017). "Serum concentrations of TNF-α, IL-6, IL-10 and TGF-β1 were measured, separately, in healthy controls and in patients with HIV-HCV coinfection, distributed in two groups, those without and those with liver cirrhosis." (PMID 23840511, 2013). "Our findings align with these observations, as evidenced by the data, which indicate that co-infection with P. berghei ANKA in previously L. major-infected animals does not result in an elevation of type 1 cytokines (IFN-γ and IL-6) observed in animals infected with P. berghei ANKA alone." (PMID 40720541, 2025). "Additionally, the median IL-6 concentration in participants co-infected with HIV was lower, at 31.77 pg mL−1 (IQR: 11.61; 77.39), compared to those without co-infection, whose median was 100.9 pg mL−1 (IQR: 35.29; 287.52), P value 0.0156." (PMID 39670465, 2025). "Besides, significantly decreased semen levels of IL-6 and IL-1β were detected in HR-HPV patients regardless of the presence of coinfections, while significantly reduced levels of IL-10 were only detected in HR-HPV+Coinf- patients." (PMID 39258253, 2024). "Conditioned medium obtained from co-infections with a non-mucoid PA isolate and HRV was able to rapidly degrade recombinant IL-6 in a serine protease-dependent manner, whereas medium from individual infections or co-infections with a mucoid isolate had no such effect." (PMID 35265536, 2022). "In addition, we assessed inflammatory gene expression in the hippocampus, and whilst TNFα was significantly increased in co-infected mice, IL-6, IL-1β and CCL-2 were not altered by single- or co-infection treatment." (PMID 29980196, 2018).
mastitis (167 papers, 2009 to 2026). Inflammation of breast tissue during lactation or postpartum due to an obstructed duct or infection. "In the mouse mastitis model, mastitis was associated with upregulated IL‐6, TNFα, and IL‐1β levels in the bloodstream, immune cell aggregation in the colon, disintegration of TJ, and poorly aligned intestinal villi." (PMID 40552401, 2025). "The upregulation of IL-6 is strongly associated with the pathophysiology of mastitis,and is found to be significantly elevated in PCM." (PMID 41019090, 2025). "The interaction between mint components and core targets shows that ursolic acid in mint is associated with TNF, IL–6, and IL–1β, reflecting its potential active role in the treatment of mastitis in dairy cows." (PMID 40005889, 2025). "IL-6 is one of the pro-inflammatory cytokines responsible for the symptoms of acute septic shock in mastitis caused by coliform bacteria." (PMID 38612339, 2024). "The aim of the study was to evaluate the concentrations of IL-6 in serum and milk from cows in the course of clinical and subclinical mastitis caused by Streptococcus spp." (PMID 38612339, 2024). "Previous studies indicate that the level of IL-6 depends on a number of factors, including the form of mastitis course, the phase of infection, and the type of microorganisms causing mastitis." (PMID 38612339, 2024). "The aim of the study was to evaluate the concentrations of Interleukin-6 (IL-6) in milk and serum of healthy cows (HE) and cows with mastitis caused by Streptococcus spp." (PMID 38612339, 2024). "Proinflammatory cytokines are involved in the pathological process of mastitis, mainly including TNF-α, IL-1β, and IL-6, which are associated with the NF-κB pathway that regulates the production of cytokines and is involved in mastitis pathogenesis." (PMID 37948460, 2023). "Previous research noted that the activation Il6–Jak2–Stat3 axis is associated with plasma cell mastitis." (PMID 37833248, 2023). "Previous studies have shown that TNF-α, IL-1β, and IL-6 are closely related to mastitis pathogenesis, and expression of these three inflammatory cytokines are significantly increased in mastitis caused by S. aureus infection." (PMID 36947494, 2023). "In addition, IFNG, IL–6, and IL–1β are also associated with at least two mint components, demonstrating that the treatment of mastitis in dairy cows with mint is the result of the synergistic action of multiple components." (PMID 40005889, 2025). "IL-6 levels in milk from healthy cows ranged from 6.09–80.2 pg/mL (median 26.6 pg/mL) and were significantly lower than in milk from all cows suffering from mastitis caused by Streptococcus spp." (PMID 38612339, 2024). "The interactions of polymorphisms in JAK2 with bovine mastitis resistance phenotypic traits (IL-17, IL-6, IL-4, IFN-γ, SCS, and SCC) show that JAK2 might be considered a useful marker in bovine mastitis resistance strategies." (PMID 33202860, 2020). "In order to characterize the expression of genes associated with immune response mechanisms to mastitis, we quantified the relative expression of the IL-2, IL-4, IL-6, IL-8, IL-10, IFN-γ and TNF- α genes in milk cells of healthy cows and cows with clinical mastitis." (PMID 21637453, 2009). "Similarly, the expression of genes related to lactation and other mammary traits (SLC38A2, SLC35B1), fertility (SLC38A2, MT1E), susceptibility to paratuberculosis, mastitis and trypanosomiasis (IL6), and feed intake/efficiency (MT1E, SLC38A2) was upregulated in Mirandesa cattle." (PMID 39333243, 2024). "The SCC and levels of generated cytokines (interleukin (IL)-1, IL-2, IL-4, IL-5, IL-6, IL-8, IL-10, and IL-12) in milk increase in both naturally occurring and experimentally induced mastitis." (PMID 40303387, 2025). "Several studies have reported that the levels of TNF-α, IL-1β, IL-6, and IL-8 in dairy cows with mastitis increase." (PMID 40266913, 2025).
mastitis (continued). "During mastitis, further cytokines are upregulated in milk, including IL-6 and IL-8, that delay programmed cell death." (PMID 40108313, 2025). "Previous studies have shown that through the activation of the NF-κB signaling pathway, miR-142 induces the release of cytokines such as TNF-α, IL-1β, IL-6, and IL-8, suggesting its pro-inflammatory role in the mastitis process." (PMID 40001538, 2025). "In other experimental studies involving mice and rats, during mastitis-induced episodes, increased levels of IL-1β, IL-6, TNF-α cytokines, and MPO were observed (see Section 4)." (PMID 41148692, 2025). "Cows with naturally occurring and experimentally induced mastitis, as well as those injected with bacterial LPS, have been shown to have relatively high levels of IL-6 in their blood and milk." (PMID 40303387, 2025). "Accordingly, a high relative transcript level of TNF-α has been observed in SCs from buffalo with subclinical mastitis followed by IL-1B, IL-6, and IFN-γ." (PMID 39858163, 2025). "miR-223 appears to participate in the TLR signaling pathway, leading to the reduced transcription and secretion of IL-1, IL-6, and IL-8, while activating innate immunity during mastitis pathogenesis, thereby mitigating inflammation." (PMID 40001538, 2025). "Following E. coli-induced mastitis in mice, G-CSF, IL-6, CXCL1, and CCL2 are released into the peritoneal fluid." (PMID 41148692, 2025). "Previous studies have indicated that TNF, IL–6, and IL–1β, as pro–inflammatory factors, are highly expressed in cows with mastitis." (PMID 40005889, 2025). "Inflammatory responses triggered by conditions such as ketosis, LDA, APM, and mastitis lead to the release of proinflammatory cytokines, including interleukin-6 (IL-6) and TNF-α." (PMID 40284849, 2025). "A recent study found that daidzein significantly alleviated LPS-induced mastitis in mouse mammary gland epithelial cells by inhibiting IL-6 and IL-1β levels and suppressing the activation of MAPK/NF-κB signaling pathways." (PMID 39199398, 2024). "The clinically explored KDM1A inhibitor GSK-LSD1 has been reported to inhibit the NF-κB-dependent production of cytokines (TNFα, IL-6, IL-1) by increasing histone H3K4me2 and H3K9me2 in LPS-induced mastitis." (PMID 39638799, 2024). "In general mastitis cases, immunoreactivity was more pronounced for IL-4, IL-6, IL-12, IL-13, IL-17A, TNF-α, and IFN-γ." (PMID 39195804, 2024). "The goal of the study was to investigate changes in the level of IL-6 in milk and serum of cows with clinical and subclinical streptococci-induced mastitis compared to healthy cows." (PMID 38612339, 2024). "The cytokine gene expression of bovine IL-6 has been demonstrated in normal mammary glands and in mastitis." (PMID 38612339, 2024). "Monitoring of IL-6 levels in milk can allow early detection of mastitis, which is especially important in cases of subclinical inflammation." (PMID 38612339, 2024). "When dairy cows have new bacterial infections over the existing mastitis, many inflammatory and immunologic cells in the body can rapidly express the IL-6 gene and produce IL-6." (PMID 39195804, 2024). "Detection of high concentrations of IL-6 in milk samples from cows affected by subclinical mastitis allows the detection of inflammation earlier than SCC." (PMID 38612339, 2024). "TNF-α increased the secretion of IL-6 and other cytokines and exacerbated mastitis-induced tissue damage through excess ROS." (PMID 38630770, 2024). "To explore the inflammatory and immune status between healthy and mastitis cows, we next performed serum TNF-α, IL-8, IL-6, IL-1, and LPS tests and found that mastitis cows had higher (p < 0.05) serum TNF-α, IL-1, and LPS concentration." (PMID 38585704, 2024). "The results of the study indicate that the content of IL-6 in the milk of mastitis cows was significantly lower than that in the serum of healthy cows (26.6 pg/mL vs. 106.3 pg/mL, p < 0.001)." (PMID 38612339, 2024).
mastitis (continued). "This study found significant differences in IL-4 and IL-6 levels in mastitis milk depending on the type of bacterial infection." (PMID 39195804, 2024). "Only in the group of cows with the subclinical form of mastitis, were the IL-6 levels in serum and milk at similar values (128.29 pg/mL vs. 165.31 pg/mL)." (PMID 38612339, 2024). "The literature suggests various immunoassay tests for early inflammation screening utilizing biomarkers like milk amyloid A, cathelicidins, myeloperoxidase enzyme of milk neutrophils, IL-6 as well as lateral flow assays for diagnosing mastitis." (PMID 38787275, 2024). "In the current study, the changes in IL-4, IL-6, and IL-10 were consistent with previous experiments, which proves that lentinan is beneficial for reducing subacute mastitis." (PMID 38731317, 2024). "This study aimed to determine the relationships of IL-4, IL-6, and IL-10 in mastitis milk with concurrent infection, bacterial pathogens, SCC, and MDA, an oxidative stress marker." (PMID 39195804, 2024). "Concomitant CNS in the streptococci mastitis quarter had the highest IL-6 level but the lowest IL-4 level." (PMID 39195804, 2024). "Gambogic acid (GA) was also reported to alleviate LPS-induced mastitis by reducing IL-6, TNF-α, and IL-1β levels." (PMID 39199398, 2024). "In 2017, average concentrations of IL-4, IL-6, and IL-10 in subclinical mastitis milk with CNS were reported as lower than the values from this study." (PMID 39195804, 2024). "Studies by a number of authors support the thesis that IL-6 can be considered a potential marker of mastitis, which is especially important when the subclinical form is difficult to notice." (PMID 38612339, 2024). "Several members of the IL gene family are involved in the regulation of dairy cow mastitis (e.g., IL6 and IL8 genes)." (PMID 39596441, 2024). "Interleukin genes play important roles in inflammation and the immune system, and some of these genes, such as IL-6, have been found to regulate the immune response in mastitis and have been identified as candidate biomarkers for subclinical mastitis." (PMID 37845761, 2023). "As expected, a significant increase in the concentrations of proinflammatory cytokines, including TNF, IL6, and IL1β, in the serum and mammary glands of clinical mastitis cases has been observed in several previous studies." (PMID 37620551, 2023). "TNF-α and IL-6 are immunoreactive in cases of mastitis, while IL-1α of the IL-1 family is more capable of driving the corresponding inflammatory response." (PMID 37189805, 2023). "In the current review, we discuss all the polymorphisms in immune- and inflammation-associated genes that are linked to mastitis resistance phenotypic traits (SCC, SCS, IL-6, IL8, IL17, and IFN-gamma)." (PMID 36911690, 2023). "The serum IL-6 in the mastitis cows was also higher than that of healthy cows, which provided a solid foundation for the current study." (PMID 37662996, 2023). "Several studies have showed that the modulation of ERK and MAPK signaling pathway can lead to anti-inflammatory role in mastitis due to the decreased release of pro-inflammatory cytokines such as tumor necrosis factor-α, IL-1β, and IL-6." (PMID 37016420, 2023). "The levels of TNF-α, IL-1β, and IL-6 in whey from cows with mastitis were significantly higher than those from normal cows (p < 0.01)." (PMID 37175449, 2023). "Data about subclinical and clinical mastitis demonstrate inflammatory responses to the intramammary infection driven by IL-1β, IL-6, and TNF-α." (PMID 36899749, 2023). "Serum IL-6 levels in the PUE-fed control healthy cows were significantly lower than those in the mastitis group (p < 0.01), and the expression of TNF-α and IL-1β also decreased, but there was no statistical significance." (PMID 37175449, 2023). "The expression of IL-6 was significantly lower in the antibiotic-treated mice compared with the mastitis-untreated group, and the expression of IL-6 was also reduced in the lipopeptide-treated group." (PMID 37189805, 2023).
mastitis (continued). "The serum TNF-α, IL-1β, and IL-6 levels of the cows with mastitis fed PUE root on day 7 were significantly lower than those on day 0 (p < 0.01), but there was no change in the healthy cows after the 7th day of the PUE addition." (PMID 37175449, 2023). "In mastitis cases, immunoreactivity was more pronounced for IL-4, IL-6, IL-12, IL-13, IL-17A, TNF-α, and IFN-γ." (PMID 35335696, 2022). "Interleukin genes play important roles in inflammation and the immune system, and some of them, such as IL6 has been found to regulate the immune response to bovine mastitis and also identified as a candidate biomarker of subclinical mastitis." (PMID 36336691, 2022). "Interleukin-6 (IL-6) is a major pro-inflammatory factor during many inflammation-related diseases including mastitis, and a quite recently identified ferroptosis inducer." (PMID 35549778, 2022). "An in vitro model of M. bovis-induced mastitis showed that the expression of IL-6, IL-8, and TNF-α increased significantly following infection." (PMID 35464378, 2022). "In order to obtain the highly sensitive and accurate detection of IL-6 for the judgement of mastitis in dairy cows, the SERS intensity of the test dot was measured using a Raman spectrometer." (PMID 35407209, 2022). "In animal models of LPS-induced mastitis, melatonin has been shown to decrease the inflammatory response by reducing oxidative stress and pro-inflammatory cytokines such as IL-1β, IL-6, GM-CSF57,58." (PMID 34400791, 2022). "It is observed that pathogenic activated NF-κB and MAPKs pathways caused overexpression of pro-inflammatory cytokines (IL-1β, IL-6, and TNF-α) in mastitis." (PMID 36145063, 2022). "Increased concentrations of TNF-α and IL-6 were detected in mice following the induction of mastitis, which indicated an ongoing inflammatory process." (PMID 35337027, 2022). "is thought to inhibit interleukin-6, interleukin-8, tumour necrosis factor-α, and the mitogen-activated protein kinase pathway; indeed, mastitis is characterized by increased interleukin-8 concentrations in milk." (PMID 35368771, 2022). "These increased inflammatory mediators such as TNF-α, IL-1ß and IL-6 contributed to the pathogenesis of mastitis." (PMID 35185907, 2022). "When mastitis occurs, the IL-6 content in the serum and milk of dairy cows will increase significantly up to 254.32 and 432.09 pg mL−1, respectively." (PMID 35407209, 2022). "When dairy cows have bacterial infections such as mastitis and endometritis, a lot of inflammatory and immunologic cells in the body can express the IL-6 gene and produce IL-6." (PMID 35407209, 2022). "Consistently, a study showed that the detection of IL-6 in milk indicated subclinical mastitis earlier than SCC." (PMID 36213405, 2022). "It has been reported that the expression of IL-6 is positively correlated with the severity of mastitis in dairy cows." (PMID 35681895, 2022). "Contrary to our findings, IL-6 levels in whey of mastitis-affected cows and subclinical mastitis group cows were shown to be higher than in samples from healthy cows." (PMID 35335696, 2022). "Lactating cows with clinical mastitis and subclinical mastitis showed a marked increase in interleukin (IL)-2, IL-6, IL-1β, and tumor necrosis factor (TNF)-α." (PMID 34827839, 2021). "LPS induces the expression of inflammatory cytokines such as TNF-α, IL-6, and IL-1β in the mammary glands, leading to mastitis in cows." (PMID 34858427, 2021). "The IL-6 content in most cows with serious mastitis is significantly higher than that in healthy cows, suggesting its relationship with mastitis." (PMID 34436243, 2021). "The research on mastitis development reported that the inflammatory factors including IL-6, IL-8, TNF-ɑ, and TLR4 are consistently altered." (PMID 35173767, 2021). "This pathway modulates the expression of many inflammation-related genes (such as inflammatory cytokines TNF-α, IL-1β, and IL-6), especially in mastitis." (PMID 32754201, 2020).